LPO (lactoperoxidase)
Description:
Heme-containing oxidoreductase which catalyzes the conversion of thiocyanate (SCN(-)) into antimicrobial agent hypothiocyanous acid (OSCN(-)) in the presence of hydrogen peroxide (H2O2). Also involved in the conversion of iodide (I(-)) into hypoiodite (IO(-)) in the presence of H2O2 (By similarity). Responsible for the inactivation of a wide range of micro-organisms and hence, important component of defense mechanism. Shows antibacterial properties against Pseudomonas aeruginosa. The lactoperoxidase-SCN(-)-H2O2 system shows antibacterial properties against Burkholderia cepacia and Haemophilus influenzae in vitro. Present in mammary and salivary gland secretions and may contribute to airway host defense against infection. May contribute to maintaining an appropriate H2O2 cellular level, therefore protecting cells from H2O2-caused injuries and inflammation (By similarity).
Synonyms: SPO
Tractability: Antibody: UniProt places it where antibodies can reach, with high confidence; its Gene Ontology location is reachable by antibodies, with high confidence; UniProt predicts a signal peptide or a membrane-spanning region. PROTAC: a small molecule that binds it is known.
Target class: Enzyme; Oxidoreductase
Gene: Protein-coding gene on chromosome 17 (58,218,548 to 58,268,518, forward strand). Ensembl gene ENSG00000167419.
Subcellular location: Secreted; Cytoplasm
Pathways (Reactome):
Immune System: Events associated with phagocytolytic activity of PMN cells
Gene Ontology:
Molecular function: peroxidase activity; thiocyanate peroxidase activity; heme binding; lactoperoxidase activity
Biological process: defense response to bacterium; detection of chemical stimulus involved in sensory perception of bitter taste; response to oxidative stress; cellular oxidant detoxification; thiocyanate metabolic process
Cellular component: basolateral plasma membrane; extracellular exosome; extracellular region; cytoplasm
Genetic constraint (gnomAD): Loss-of-function variants: 71 observed, 70.13 expected, observed/expected ratio (o/e) 1.01, 90% interval 0.83 to 1.23. The upper end of that interval is the gene's LOEUF score, 1.23, which puts it in group 5 of 6, group 1 being the genes least tolerant of losing a copy. Missense variants: 870 observed, 935.51 expected, observed/expected ratio (o/e) 0.93, 90% interval 0.88 to 0.98. Synonymous variants: 360 observed, 369.62 expected, observed/expected ratio (o/e) 0.97, 90% interval 0.89 to 1.06.
Homologues: Orthologues: chimpanzee LPO (99% identical), macaque LPO (98% identical), pig LPO (87% identical), dog LPO (86% identical), guinea pig LPO (85% identical), rabbit LPO (84% identical), mouse Lpo (79% identical), rat Lpo (79% identical), zebrafish epx (41% identical), Drosophila melanogaster Pxn (36% identical), Caenorhabditis elegans pxn-1 (36% identical), Caenorhabditis elegans pxn-2 (33% identical), and 5 more. Paralogues in human: EPX (52% identical), MPO (52% identical), TPO (42% identical), PXDN (38% identical), PXDNL (35% identical).
Diseases named in the same sentence as LPO in open-access papers:
LPO is named in the same sentence as 61 diseases in open-access papers, as found by Europe PMC text mining. Sharing a sentence is not in itself a finding about the gene and the disease. The quoted sentences say what the papers report.
breast cancer (11 papers, 2013 to 2025). A primary or metastatic malignant neoplasm involving the breast. "Low or undetectable levels of LPO in the normal mammary gland and increased expression levels in breast cancer tissue has been already reported by others." (PMID 29513734, 2018). "This is consistent with the Western blot results which showed that LPO was expressed in breast cancer tissue and in the human lung tissue used as a positive control." (PMID 29513734, 2018). "Contrarily, increasing n6/n3 fatty acid ratios induced a significant increase in LPO not only in breast cancer cells but also in MCF10A compared to the untreated control cells (p<0.001)." (PMID 26325577, 2015). "Lactoperoxidase, heme containing enzyme produced in mammary glands, has been proposed to be involved in breast cancer." (PMID 23762435, 2013). "Finally, a breast cancer-specific mechanism for ROS generation has been proposed, called estrogen hormone metabolism by lactoperoxidase." (PMID 38785550, 2024). "Moreover, it has been found that LPO is engaged in breast cancer etiology due to its ability to activate heterocyclic amines belonging to environmental and dietary carcinogens." (PMID 38074096, 2023). "We found that LPO was expressed in all the tested breast cancer samples." (PMID 29513734, 2018). "Anti-TPO antibodies might initiate chronic inflammation and destruction of mammary cells via cross-reactivity with lactoperoxidase, but generation of oxidative stress by lactoperoxidase activity alone might also promote breast cancer." (PMID 28536577, 2017). "Cross-reactivity with lactoperoxidase leading to induction of chronic inflammation might promote breast cancer, while anti-thyroid antibodies in manifest breast cancer might be an indication for a more active immune system." (PMID 28536577, 2017). "A causative role of chronic inflammation might also be deduced in breast cancer development since anti-TPO antibodies are able to cross-react with lactoperoxidase and initiate the inflammatory process." (PMID 28536577, 2017). "Thus, there was increase in LPO activity in breast cancer cells compared to untreated control cells, the increase being more pronounced in MDA-MB-231 compared to MCF7." (PMID 26325577, 2015). "The LPO level significantly increased in patients with stage III and IV breast cancer, and the activity of GPx and SOD enzymes in serum samples of breast cancer patients decreased compared with healthy controls." (PMID 34885171, 2021). "In a different human mammary cancer model, using dimethylbenz[a]anthracene (DMBA)-induced mammary tumors, the tumor cells were shown to express both NIS and LPO." (PMID 34960019, 2021). "The protective effect of 0.1% KI is lost when the enzyme lactoperoxidase (LPO), which is present in mammary cancers, is inhibited by MMI, indicating that I− from KI needs to be oxidized to have the apoptotic effect." (PMID 33513754, 2021). "In both breast cancer cell lines, MCF-7 and MDA-MB-231, the LPO protein was found to be localized in the cytoplasm and in the nucleolus." (PMID 29513734, 2018). "Here we show the LPO protein expression in breast cancer cell lines and breast tissue samples, while the peritumoral sections and the normal breast cell line were not positive for LPO." (PMID 29513734, 2018).
mastitis (8 papers, 2014 to 2025). Inflammation of breast tissue during lactation or postpartum due to an obstructed duct or infection. "Promkot and Wanapat9 previously demonstrated that the milk thiocyanate concentration and somatic cell count in the milk can be activated by lactoperoxidase as an indication of mastitis." (PMID 35264651, 2022). "In this context, this methodology was developed based on the lactoperoxidase activity to assess mastitis using recorded images of a cuvette during a simple experiment and subsequent image treatments with an R statistics platform." (PMID 35176036, 2022). "LPO is known to exert antimicrobial effects and was previously reported as a biomarker of mastitis due to its role as an innate immune effector molecule." (PMID 29283389, 2017). "A study from 2022 showed that LPO activity may be measured to determine the mammary gland health of cows due to LPO activity increases when mastitis occurs in cows." (PMID 40507866, 2025). "Lactoperoxidase, an enzyme involved in the innate immune defense of the mammary gland, is secreted by the epithelial cells in response to a microbial challenge, indicating its potential utility as a biomarker for mastitis detection." (PMID 39456911, 2024). "Therefore, lactoperoxidase can be quantified by this method and contribute as an evaluative parameter in determining mastitis in dairy cows." (PMID 35176036, 2022). "In addition, to further evaluate the potential of the lactoperoxidase system and somatic cell count using an accessible and economical method by image analysis to detect mastitis in dairy cows." (PMID 35176036, 2022).
dental caries (4 papers, 2021 to 2024). The decay of a tooth, in which it becomes softened, discolored, and/or porous. "The lactoperoxidase (LPO) system shows promise in the prevention of dental caries, a common chronic disease." (PMID 37569513, 2023). "In bacterial diseases such as dental caries, lactoperoxidase is oxidized to a form known as Compound II, which is characterized by its inability to oxidize SCN–, resulting in a decreased generation of antimicrobial products." (PMID 33926051, 2021).
periodontitis (4 papers, 2015 to 2020). An acute or chronic inflammatory process that affects the tissues that surround and support the teeth. "Considering that the effects of milk-derived lactoperoxidase in periodontitis possibly go beyond the antibacterial activity, a role of lactoperoxidase in oral health is possible." (PMID 32246075, 2020). "Commercially available dentifrices containing lactoperoxidase have been subjected to clinical trials involving participants from various age groups with various clinical conditions, e.g., malodor, xerostomia, caries, and chronic periodontitis, as well as healthy subjects." (PMID 30901933, 2019).
asthma (3 papers, 2007 to 2024). "This indicates the role of lactoperoxidase in scavenging of hydrogen peroxide and in asthma pathogenesis." (PMID 19727356, 2007). "The purpose of the present study was to determine the contribution and the role of lactoperoxidase in scavenging airway hydrogen peroxide, in order to propose a therapeutic approach for asthma." (PMID 19727356, 2007). "In conclusion, this study indicated that airway lactoperoxidase may play an important role in the scavenging of hydrogen peroxide damage in asthma." (PMID 19727356, 2007). "TPO and LPO are expressed by airway epithelial cells, and we found that TPO gene expression is increased in airway epithelial cells from patients with asthma, especially in those with airway mucus plugging." (PMID 38889046, 2024). "To begin to explore the clinical implications of epithelial cell peroxidase activity for airway mucus plug pathology in asthma, we examined gene expression for LPO and TPO in epithelial brushings from patients with asthma in the Severe Asthma Research Program-3 (SARP-3)." (PMID 38889046, 2024). "Additionally, when we used the mucus plug score data from the CT lung scans, we found no increase in epithelial cell LPO gene expression in asthma patient subgroups with high mucus plug scores." (PMID 38889046, 2024). "Asthmatic patients who were treated with lactoperoxidase aerosol showed lower disease activity and reduced damaging effects of hydrogen peroxide (H2O2), which is mainly generated by neutrophils and eosinophils in asthma and contributes to airway damages and inflammation." (PMID 28858242, 2017). "When we used the RNA-Seq database to determine the expression of LPO and TPO in asthma, we found that TPO expression was significantly higher in patients with asthma than in healthy individuals, whereas expression of LPO was not." (PMID 38889046, 2024).
colorectal cancer (3 papers, 2015 to 2025). A primary or metastatic malignant neoplasm that affects the colon or rectum. "Specifically, loss of hsa-miR-10a that targets KLF4, as seen in STIM1 overexpression patients, led to upregulation of LPO and initiation of colorectal carcinomas." (PMID 26543234, 2015).
colon cancer (2 papers, 2017 to 2024). "After that, the purified LPO was immobilized on the modified GO-SA nano-composite to form a novel nano-combination of GO-SA-LPO as a potent anticancer agent against colon cancer as an in vitro study." (PMID 39438495, 2024). "Our data show that treatment of colon cancer cells with Andro induces ROS production in addition to LPO, TRX, and GPX antioxidant response genes." (PMID 28412728, 2017).
COVID-19 (2 papers, 2022 to 2026). A disease caused by infection with severe acute respiratory syndrome coronavirus 2. "Carriers of LPO variants thus had an increased risk of developing severe COVID-19." (PMID 41500120, 2026). "Finally, the integration of the two omics approaches (exome- and transcriptome-based) pinpointed a single gene, LPO, which was significantly enriched in damaging rare variants in patients with COVID-19, and was also significantly upregulated in ICU-admitted individuals." (PMID 41500120, 2026). "Research by the New Zealand pharmaceutical producer Quantec showed that a protein complex containing LF and lactoperoxidase, obtained from fresh pasteurized cow milk, can protect human cells against COVID-19." (PMID 36613286, 2022). "Quantec noted that the use of a complex of milk proteins yielded better results against COVID-19 than pure LF or lactoperoxidase." (PMID 36613286, 2022). "We propose that LPO haploinsufficiency may impair host capacity to neutralise ROS, contributing to COVID-19 progression." (PMID 41500120, 2026). "Association meta-analysis of common variants within LPO revealed 59 nominally associated (p < 0.05) single nucleotide polymorphisms (SNPs) with patients with severe COVID-19 compared to individuals with COVID-19 negative/unknown status." (PMID 41500120, 2026).
influenza (2 papers, 2018 to 2026). An acute viral infection of the respiratory tract, occurring in isolated cases, in epidemics, or in pandemics; it is caused by serologically different strains of viruses (influenzaviruses) designated A, B, and C, has a 3-day incubation period, and usually lasts for 3 to 10 days. "Our central focus has been to address the question of whether SCN- or I- serves as a better substrate for the anti-influenza action of LPO." (PMID 30044776, 2018). "We selected data on all infectious diseases and on paediatric long COVID, and observed that LPO levels were significantly increased (p < 0.05, log2(fold-change) ≥0.5) in all infections characterised by pulmonary symptoms, with higher expression in influenza cases." (PMID 41500120, 2026).
intestinal infections (2 papers, 2013 to 2025). "Lysozyme, lactoperoxidase and lactoferrin have been recognized as antimicrobial and bacteriostatic agents and could be useful to prevent intestine infections in infants." (PMID 28239105, 2013).
periodontal disease (2 papers, 2019 to 2024). "In accordance with the literature, our study supports that the lower abundance of Lactoperoxidase might contribute to deteriorated defense against microorganisms associated with caries, periodontal disease, and fungal infections." (PMID 39640734, 2024).
allergies (1 paper, 2022). "The main components of CM, such as lysozyme, Lf and lactoperoxidase are important in the treatment of some inflammatory diseases, including hepatitis, allergies, lactose intolerance and liver damage caused by alcohol in some parts of the world." (PMID 35493477, 2022).
Chagas disease (1 paper, 2013). A parasitic infection caused by Trypanosoma cruzi. "The MPO, LPO and nitrite are excellent biomarkers for diagnosing seropositive/chagasic subjects, and MPO and LPO levels have potential utility in identifying clinical severity of Chagas disease." (PMID 23951383, 2013). "The finding of a significant correlation between the increase in MPO and LPO levels and clinical Chagas disease in this study provide us an impetus to test and verify the sensitivity and specificity of MPO and LPO in determining clinical Chagas disease in large-scale cross-sectional studies." (PMID 23951383, 2013).
chronic bronchitis (1 paper, 2014). A type of chronic obstructive pulmonary disease characterized by chronic inflammation in the bronchial tree that results in edema, mucus production, obstruction, and reduced airflow to and from the lung alveoli. "In a similar animal study the increased levels of IL6, IL8 and LPO (lipoperoxide) in smokers with chronic bronchitis is compared with non-smokers." (PMID 25031491, 2014).
Cognitive impairment (1 paper, 2019). Abnormal cognition is characterized by deficits in thinking, reasoning, or remembering. "Thus, the involvement of oxidative stress in BPA induced cognitive impairment was assessed using various parameters like catalase, SOD and LPO in the hippocampal region of mice." (PMID 31064381, 2019).
colitis (1 paper, 2021). Inflammation of the colon. "Third, comparing to other antioxidants, such as catalase and lactoperoxidase used for the treatment of colitis, r-Alb has several advantages." (PMID 33601276, 2021).
cystic fibrosis (1 paper, 2011). Autosomal recessive disorder caused by pathogenic variants in the CFTR gene (cystic fibrosis transmembrane conductance regulator), which encodes a chloride and bicarbonate channel expressed in epithelial cells, and follow the diagnosis criteria. "But under certain pathological conditions such as cystic fibrosis, the level of SCN− is known to be, as low as, 0.5 μM which disrupts the microbicidal function of LPO." (PMID 22132121, 2011).
dementia (1 paper, 2022). Loss of intellectual abilities interfering with an individual's social and occupational functions. "This includes increased LPO production, decreased tGSH concentration, and changed SOD activity in the brain of rats with experimental dementia." (PMID 35204256, 2022).
depression (1 paper, 2025). "Subsequently, we employed Mendelian randomization analysis to identify IL1R1 and LPO as protective factors against depression." (PMID 40343008, 2025).
dry eye (1 paper, 2022). "Lactoperoxidase had its lowest concentration in patients with dry eye compared with healthy controls and patients with MGD." (PMID 35685417, 2022). "A recent study on tears proteomic analysis showed different sets of proteins that differentiate between MGD and dry eye comprising antileukoproteinase, phospholipase A2, and lactoperoxidase." (PMID 35685417, 2022).
follicular adenoma (1 paper, 2012). "For example, in case of human thyroid diseases – non-toxic nodular goitre, carcinomas (follicular and papillary) and follicular adenoma – the highest level of LPO products was found in carcinomas; interestingly, it was also increased in follicular adenoma." (PMID 23270549, 2012).
Hyperglycemia (1 paper, 2022). An increased concentration of glucose in the blood. "Clusters of CNCs encapsulating glucose oxidase (Gox; Gox-CNCs) and lactoperoxidase (LPO; LPO-CNCs) can be used for a cascade reaction that functions as protection from lung infections, treatment of hyperglycemia, and reactive oxygen species (ROS) therapy." (PMID 35628527, 2022).
kidney cancer (1 paper, 2023). Primary or metastatic malignant neoplasm involving the kidney. "Thus the upregulation of LPO, together with OXPHOS imbalance, observed after BPA-treatment, may contribute to the increased risk of kidney cancer development." (PMID 38074096, 2023).
Obesity (1 paper, 2025). Accumulation of substantial excess body fat. "In the absence of the LPO gene, there is an increase in the frequency of diverse diseases, including inflammation, tumor formation, and obesity." (PMID 40507866, 2025).
oral squamous cell carcinoma (1 paper, 2020). "In summary, we show here that milk and lactoperoxidase but not dairy products change gene expression in oral squamous cell carcinoma cells thereby adding a piece of knowledge to our understanding of the possible role of milk in oral oncology." (PMID 32246075, 2020).
Parkinson disease (1 paper, 2014). A progressive degenerative disorder of the central nervous system characterized by loss of dopamine producing neurons in the substantia nigra and the presence of Lewy bodies in the substantia nigra and locus coeruleus. "Lactoperoxidase present in the brain (brain peroxidase) play an important role in different metabolic events associated with Parkinson’s disease." (PMID 25168993, 2014). "Role of LPO in Parkinson’s disease is confirmed as the cytotoxic activity of this enzyme is fully inhibited by neuroactive compounds like dopamine, reduced glutathione, and L-cysteine." (PMID 25168993, 2014).